SAMHD1 (SAM and HD domain containing deoxynucleoside triphosphate triphosphohydrolase 1)
Diseases named in the same sentence as SAMHD1 in open-access papers (continued):
Sharing a sentence is not in itself a finding about the gene and the disease.
viral infection (88 papers, 2010 to 2025). "While SAMHD1 is associated with the immune response to viral infections, little is known about its possible role in immunity against bacterial pathogens." (PMID 40352920, 2025). "For SAMHD1, the enriched pathways mainly were associated with viral infections, implying a dominant effect of genetic alterations in SAMHD1 on infectious diseases." (PMID 35633950, 2022). "Since loss of SAMHD1 results in an innate immune response overlapping pathways associated with viral infections, it is important to note that the antiviral responses (e.g., CHIKV) in zebrafish share similarities with those identified in mammals." (PMID 32244340, 2020). "Along with phosphorylation of T592, the ability of SAMHD1 to undergo redox transformations has been implicated in its ability to restrict viral infection." (PMID 32244340, 2020). "Indirect immunofluorescence assays further supported the CRL-mediated SAMHD1 loss at late stages of virus infection." (PMID 32850489, 2020). "Knockdown of CUL2 and to a lesser extent CUL1 using siRNA stabilized SAMHD1 in normal fibroblasts and inhibited SAMHD1 loss during virus infection." (PMID 32850489, 2020). "SAMHD1WT or SAMHD1D137N alone effectively reduced F-MLV infectivity, while the catalytic mutant (D207N) and RNase-deficient (Q548A) SAMHD1 lost the ability to control the viral infection." (PMID 26032178, 2015). "Even though the sensitivity of retroviruses to SAMHD1 differs slightly, suboptimal substrate conditions caused by SAMHD1 play a crucial role in limiting viral infections." (PMID 26032178, 2015). "We observed that SAMHD1-mediated FIV restriction was tightly associated with FIV genomic RNA levels following viral infection, supporting RNase-mediated control by SAMHD1." (PMID 26032178, 2015). "SAMHD1 knock-down caused a 1.5-2.8-fold increase in luciferase reporter virus infection and a 1.6-fold increase in the number of cells infected by the GFP reporter virus." (PMID 24586870, 2014). "By contrast, SIVsm and HIV-2 encode Vpx to overcome SAMHD1-mediated restriction, which likely induces protective innate immunity to confine viral infection in natural hosts." (PMID 24523981, 2013). "While Samhd1 is linked to the immune response in viral infections, it may play a previously unknown role in immunity against bacterial pathogens." (PMID 35417454, 2022). "It suggested that enhancement of SAMHD1 may be associated with the initiation of innate immunity against viral infection." (PMID 36341359, 2022). "SAMHD1 is a protein, encoded by AGS5, that is upregulated in response to viral infections and may have a regulator role on immune system and cerebral vascular homeostasis." (PMID 22883345, 2012). "To determine whether cells with a nonsense mutation in SAMHD1 obtained from AGS patients might be more susceptible to viral infection, we tested HIV-1 infectivity in PBMC from two related AGS patients described previously." (PMID 22174685, 2011). "It has also been suggested that SAMHD1 negatively regulates interferon (IFN) and the inflammatory responses to viral infections; however, the functions and mechanisms of SAMHD1 in modulating innate immunity are still under study." (PMID 40352920, 2025). "This feature has been widely studied in viral infection systems to elucidate the restriction mechanism of SAMHD1, with different, even contradictory, results being obtained depending on the pathogen used." (PMID 40352920, 2025). "SAMHD1 is a protein that plays a critical role in the immune response against viral infections, its deoxynucleoside triphosphate (dNTP) triphosphohydrolase (dNTPase) activity being one of its most studied antiviral characteristics." (PMID 40352920, 2025). "The results showed that SIVmac239-WT-GFP virus infection decreased the expression of SAMHD1 in the USP37 knockdown group when compared to that in the control group." (PMID 39655951, 2025).
viral infection (continued). "SAMHD1 restricts HCMV replication since an increase in viral gene expression and viral infection was observed upon depletion of SAMHD1 expression in human fibroblasts and myeloid cells." (PMID 40277359, 2025). "Beyond its direct antiviral activities, SAMHD1 has been suggested to play a role in the suppression of the innate immune responses to viral infections and inflammatory stimuli." (PMID 40352920, 2025). "While previous studies have focused on the role of SAMHD1 in modulating the immune responses to viral infections, the findings of this study highlight its importance in bacterial immunity." (PMID 40352920, 2025). "We have previously shown that SAMHD1 suppresses NF-κB activation and type I interferon activation induced by virus infections and inflammation through interaction with the key proteins in their respective pathways (17, –, 19)." (PMID 40434097, 2025). "Previously, it was discovered that SAMHD1 activity protects monocytes and macrophages from viral infection by degrading dNTPs." (PMID 40259927, 2025). "The RNA level of SAMHD1 in A549 cells also showed a trend of first increasing and then decreasing after virus infection." (PMID 38287375, 2024). "Host factors such as SAMHD1 and A3G are crucial in defending against viral infections like HIV‐1 by disrupting various stages of the viral replication process." (PMID 39702696, 2024). "For instance, the genetic loss of SAMHD1 leads to heightened interferon activation, suppressing SARS-CoV-2 replication, indicating its role in modulating immune responses during viral infection." (PMID 39339888, 2024). "SAMHD1 is a host-limiting immune factor that inhibits viral infection and replication by hydrolyzing intracellular dNTPs." (PMID 37504299, 2023). "For instance, the sterile alpha motif and HD-domain-containing protein 1 (SAMHD1) are able to block inflammatory responses and the activation of retroviruses during viral infections." (PMID 36826024, 2023). "In this study, we found that SAMHD1 inhibited IKKα- and IKKβ-mediated NF-κB activation in cells upon viral infection or inflammatory stimulation." (PMID 37100289, 2023). "SAMHD1, a dNTPase protecting cells from viral infections, has been recently found to participate in DNA damage repair process." (PMID 37081042, 2023). "Our findings revealed new mechanisms by which SAMHD1 suppresses IFN-I induction through the MAVS, IKKε, and IRF7 signaling axis in the context of viral infection, which help better understand the role of SAMHD1 in innate immunity." (PMID 37328105, 2023). "Overall, our findings reveal a new regulatory mechanism by which SAMHD1 inhibits NF-κB activation during viral infection and inflammation." (PMID 37100289, 2023). "Transdifferentiated BLaER1 cells harbor active dephosphorylated SAMHD1 that blocks HIV-1 reporter virus infection." (PMID 37800914, 2023). "SAMHD1 protects cells from viral infections and operates at stalled replication forks to prevent IFN induction, a significant regulator of dNTP concentrations in human cells." (PMID 36362045, 2022). "The STRING database revealed that three possible target proteins interacted with SLFN, including BST2, SAMHD1, and TRIM5, previously implicated in viral infection." (PMID 36090985, 2022). "Given the potential utility of inactivating SAMHD1 in cancer to enhance the efficacy of antimetabolites, coupled with potential applications in the immune response and viral infections, various approaches have been reported to target SAMHD1." (PMID 35583750, 2022). "SAMHD1 controls viral infection through innate and adaptive immunity at the level of the infected cell." (PMID 36362045, 2022). "Restored lipid level by overexpression of SREBP1 or supplement with LDs counteracts with the antiviral activity of SAMHD1, providing evidence supporting the role of SAMHD1-mediated down-regulation of lipid synthesis in its function to inhibit viral infection." (PMID 36532074, 2022).
viral infection (continued). "SAMHD1 is a deoxynucleoside triphosphohydrolase that can suppress the innate immune response to viral infection by interacting with various key proteins in the immune signaling pathways." (PMID 36145314, 2022). "The DCAF1 E3 ligase has been reported to be hijacked by Vpx or Vpr to degrade SAMHD1 in immune cells upon viral infection." (PMID 35803902, 2022). "We recently reported that SAMHD1 regulates the innate immune response through the suppression of nuclear factor-κB (NF-κB) activity induced by viral infections and inflammatory stimuli." (PMID 33177202, 2021). "Experiments in mice revealed that SAMHD1 also inhibits pseudotyped single-cycle HIV-1 reporter virus infection in vivo." (PMID 33801276, 2021). "SAMHD1 also suppresses the activation of NF-κB in response to viral infections and inflammatory stimuli." (PMID 33177202, 2021). "Grass carp DDX41 and SAMHD1 are located in the nucleus, but they are translocated from the nucleus to the cytoplasm in response to virus infection." (PMID 33488591, 2020). "The generation of SAMHD1-defficient mice has been useful in studying the role of SAMHD1 in the immune response and during viral infection." (PMID 32244340, 2020). "Altogether, our results demonstrate that SAMHD1 inhibits the growth of HCMV, but HCMV causes degradation of SAMHD1 at late stages of viral infection through the CRL complexes." (PMID 32850489, 2020). "SAMHD1 protects cells from viral infection and is involved in the development of cancer and chronic inflammation." (PMID 31151297, 2019). "The SAMHD1 gene was first identified in human dendritic cells as an ortholog of the mouse gene, Mg11 induced by interferon-γ upon viral infection." (PMID 29342871, 2018). "In live cells, the effects of SAMHD1 phosphorylation were investigated by ectopic over-expression of SAMHD1 mutants and the restriction of viral infection or dNTP pool decrease, both readouts of SAMHD1 activity." (PMID 30039733, 2018). "The identification of SAMHD1 as a regulator of the innate immune response to viral infection has led to the development of an exciting field of research." (PMID 29176984, 2017). "Here, we review and analyze the latest literature on the antiviral function of SAMHD1, including the mechanism of HIV-1 restriction and the ability of SAMHD1 to regulate the innate immune response to viral infection." (PMID 29176984, 2017). "As such, while SAMHD1 seems to play a key role in a strategy of the immune system to avoid immune cellular responses upon viral infection, it also represents a key difference between the HIV infection of human patients and the NHP animal model." (PMID 26858716, 2016). "In summary, the demonstration that phosphorylation of IRF3 contributes to inducing upregulation of SAMHD1 expression has important consequences for understanding host innate immunity and in the future management of virus infection." (PMID 27411355, 2016). "A first hint at the possibility that SAMHD1 prevents sensing of virus infection came from its implication in AGS, a rare autoinflammatory disease characterized by chronic IFN production." (PMID 27477283, 2016). "In order to eliminate the effect of IFN-α on SAMHD1 expression in the context of viral infection, we further analyzed the expression of IFN-α in PRRSV infected PAMs." (PMID 27411355, 2016). "SAMHD1 is a deoxynucleoside triphosphohydrolase that interferes with viral infection mostly by limiting the intracellular concentrations of dNTPs, while A3A is a cytidine deaminase that has been described to edit incoming vDNA." (PMID 26496699, 2015). "In that experiment, SAMHD1 was reported to block virus infection in resting human CD4+ T lymphocytes unless SIVmac239 Vpx was co-packaged into an HIV-1 expressing GFP construct." (PMID 25996507, 2015). "Several lines of evidence implicate SAMHD1 in immune function, as it is upregulated in response to viral infections and is thought to play a role in mediating TNF-α proinflammatory responses." (PMID 26504826, 2015).
viral infection (continued). "Recent studies of SAMHD1 during HIV infection have significantly increased our understanding of its important role in restricting viral infections, as well as its biochemical functions." (PMID 26504826, 2015). "While HIV-1 genomic RNA is a potent target for SAMHD1 during viral infection, the specificity of SAMHD1-mediated RNase activity during infection by other viruses is unclear." (PMID 26032178, 2015). "We found that endogenous mouse SAMHD1 restricts not only HIV-1 but also MLV reporter virus infection at the level of reverse transcription in primary myeloid cells." (PMID 26667483, 2015). "The mechanism of REAF anti-viral activity shares similarities with known restriction factors APOBEC, tetherin and SAMHD1 and is an important new addition to the cellular armoury against viral infection." (PMID 24410916, 2014). "Here we explore the potential interplay between the role of IFN-α during the early steps of viral infection and the mechanism of nucleotide depletion governed by SAMHD1." (PMID 23497353, 2013). "Additional ex vivo virological and immunological studies using myeloid cells and CD4+ T-cells from HIV-1 infected individuals are required to better understand the role of SAMHD1 in viral infection." (PMID 24523981, 2013). "For instance, one can use pharmacologic induction of low dNTP pools in HIV-1 target cells to inhibit viral infection or to block SAMHD1 activity to elicit protective anti-HIV-1 immune responses." (PMID 23092163, 2012). "Overall, viral RNR and cellular SAMHD1 play multifaceted roles in regulating viral infections." (PMID 39339888, 2024). "Therefore, it is of interest to understand the mechanism by which SAMHD1 exerts its suppression of the IFN-I pathway during virus infection." (PMID 37328105, 2023). "SAMHD1 also suppresses NF-κB activation induced by inflammatory stimuli and viral infections." (PMID 37100289, 2023). "Other research shows that SAMHD1 may inhibits activation of NF-κB during virus infection by directly binding to NF-κB1/2 and reducing phosphorylation of the NF-κB inhibitory protein IκBα or through a negative regulation of TRAF6-TAK1 checkpoint." (PMID 37175593, 2023). "In addition, the virus-derived protein VPX can hijack the Cul4-DDB1-DCAF1 E3 ligase complex and mediate the degradation of SAMHD1, facilitating viral infection." (PMID 35803902, 2022). "Samhd1 regulates interferon pathways in response to viral infections through NF-KB." (PMID 35417454, 2022). "However, this strategy of protecting host from virus infection through depletion of dNTPs hardly explains the entirety of SAMHD1’s antiviral functionality." (PMID 36532074, 2022). "Exploring how SAMHD1 contributes to this balance may provide insights toward the development of new treatment strategies to clear viral infections or control inflammatory diseases." (PMID 33177202, 2021). "In our analyses, there was an increase in IFIH1, SAMHD1, MX1during viral infection, which might be due to the early stage of infection." (PMID 32566414, 2020). "Our results confirm and expand the number of drugs whose efficacy might be affected by SAMHD1 function, demonstrating the importance of SAMHD1 for targeted health therapies including nucleoside analogues such as treatments for cancer and viral infections." (PMID 32197329, 2020). "Transcript levels of SAMHD1 increase over time and stay elevated when the cells undergo rapid rounds of cell division and DNA replication, suggesting that high levels of both MRE11A and SAMHD1 limit DRS in this phase of viral infection and later when lymphoblastoid cell lines emerge." (PMID 31530670, 2019). "The effect of SAMHD1 on IFN-I induction during viral infection should be further studied in vivo." (PMID 29176984, 2017). "We compared SAMHD1 expression levels following treatment with IFN-α or virus infection in multiple cell lines and found that type I IFN could also regulate the expression of SAMHD1 in MARC-145 cells and porcine macrophages." (PMID 27411355, 2016).
viral infection (continued). "Then, we sought to demonstrate whether SAMHD1 induction is one of the early cellular responses to viral infection." (PMID 27411355, 2016). "The mechanism by which SAMHD1 blocks viral infection, however, is controversially discussed." (PMID 26667483, 2015). "Using SIVmac carrying a mutated Vpx gene with a single amino acid change that prevents it from binding to DCAF1 and subsequently mediating the degradation of SAMHD1, we show that virus infection of CD4+ T lymphocytes is markedly compromised both in vitro and in vivo." (PMID 25996507, 2015). "As SAMHD1 restricts viral infection to a greater extent in naïve CD4+ T cells compared with memory cells, we speculated that it could further reduce double infection of TN cells and drive the observed subset differences between single and double infection." (PMID 26559763, 2015). "Although the HIV-1 genome does not encode Vpx, most studies assessing Vpx degradation of SAMHD1 during virus infections have utilized pseudotyped HIV-1 constructs, in combination with SIV VLPs expressing Vpx, in single-cycle replication assays." (PMID 25996507, 2015). "These earlier observations suggested that SAMHD1 could play a role in innate immune response to viral infection." (PMID 23254112, 2012). "In addition, it has been shown that downregulation of p21 strongly enhances the phosphorylation of SAMHD1, resulting in increased HIV-1 proviral DNA synthesis and virus infection, and strongly suggesting that p21 levels positively correlate with the extent of SAMHD1-mediated HIV-1 restriction." (PMID 39000271, 2024). "Early studies defined a role for SAMHD1 in regulating dNTP pools in proliferating mammalian cells, but more recent findings have revealed that SAMHD1 may also suppress innate immune responses to viral infection." (PMID 35602594, 2022). "Indeed, many HIV-1 antiviral factors are involved in the NF-κB innate signaling pathway by mediating NF-κB-dependent immune responses (i.e., TRIM5α, Tetherin), or responding to NF-κB (i.e., APOBEC3G), or controlling viral infections and inflammatory diseases (i.e., SAMHD1)." (PMID 32595622, 2020). "This antagonistic relationship between SAMHD1 and innate and adaptive immune responses is of importance for our understanding of lentiviral pathogenicity, and it may provide therapeutic opportunities to control viral infections." (PMID 27477283, 2016). "The relatively high levels of expression of unphosphorylated endogenous SAMHD1 measured in memory CD4+ T lymphocytes suggested that SAMHD1 might significantly restrict viral infections in vivo, reduce virus production systemically, and affect disease progression if not adequately suppressed by Vpx." (PMID 25996507, 2015). "The inhibition of SAMHD1 by Nt-AIs may not only raise the level but also alter the balance of the intracellular dNTP pool, as observed in AGS patients, resulting in increased DNA damage and a greater susceptibility to viral infection." (PMID 25331707, 2015). "SAMHD1 can suppress the NF-kB and IFN-I signaling pathways in response to pro-inflammatory stimuli and viral infections." (PMID 39000325, 2024). "We have shown that SAMHD1 suppresses nuclear factor kappa-B activation and type I interferon (IFN-I) induction by viral infection and inflammatory stimuli." (PMID 37328105, 2023). "We have demonstrated that SAMHD1 suppresses nuclear factor kappa-B and IFN-I signaling pathways in response to pro-inflammatory stimuli and virus infections." (PMID 37328105, 2023). "SAMHD1 has been suggested as a way to down-regulate IFN and inflammatory responses to viral infections." (PMID 37371788, 2023). "We have reported that SAMHD1 suppresses NF-κB activation and type I interferon (IFN-I) activation induced by inflammatory stimuli and viral infections, suggesting that SAMHD1 plays a significant role in modulating innate immunity." (PMID 37100289, 2023).